LRRC28 (leucine rich repeat containing 28)
Synonyms: MGC24976; FLJ34269; FLJ45242
Tractability: PROTAC: ubiquitination databases record sites on it.
Gene: Protein-coding gene on chromosome 15 (99,250,937 to 99,390,729, forward strand). Ensembl gene ENSG00000168904.
Subcellular location (Human Protein Atlas): Nucleoplasm; Golgi apparatus; Mitochondria
Gene Ontology:
Biological process: intracellular signal transduction
Genetic constraint (gnomAD): Loss-of-function variants: 26 observed, 36.51 expected, observed/expected ratio (o/e) 0.71, 90% interval 0.52 to 0.99. The upper end of that interval is the gene's LOEUF score, 0.99, which puts it in group 4 of 6, group 1 being the genes least tolerant of losing a copy. Missense variants: 398 observed, 418.09 expected, observed/expected ratio (o/e) 0.95, 90% interval 0.88 to 1.03. Synonymous variants: 192 observed, 175.34 expected, observed/expected ratio (o/e) 1.1, 90% interval 0.97 to 1.23.
Homologues: Orthologues: chimpanzee LRRC28 (99% identical), macaque LRRC28 (99% identical), guinea pig LRRC28 (96% identical), rat Lrrc28 (91% identical), mouse Lrrc28 (90% identical), rabbit LRRC28 (87% identical), tropical clawed frog lrrc28 (81% identical), zebrafish lrrc28 (70% identical). Paralogues in human: SCRIB (30% identical), LRRC1 (28% identical), LRCH2 (26% identical), LRRC7 (26% identical), ERBIN (26% identical), LRRC8A (25% identical), MFHAS1 (25% identical), LRCH4 (25% identical), PHLPP2 (25% identical), PIDD1 (25% identical), LRCH3 (24% identical), LRRC8B (24% identical), and 19 more.
Diseases named in the same sentence as LRRC28 in open-access papers:
LRRC28 is named in the same sentence as 1 disease in open-access papers, as found by Europe PMC text mining. Sharing a sentence is not in itself a finding about the gene and the disease. The quoted sentences say what the papers report.
tumor (1 paper, 2023). "The most significant CRISPRi screened enhancer E_349 interacts with MEF2A and LRRC28 instead of its designed target IGF1R, which implies that HRR-associated enhancers could modulate multiple uncharacterized melanoma cancer genes for tumor survival." (PMID 37904237, 2023).